MIR4779 (microRNA 4779)
Synonyms: hsa-mir-4779
Gene: MicroRNA gene on chromosome 2 (86,193,026 to 86,193,108, reverse strand). Ensembl gene ENSG00000265420.
Homologues: Orthologues: chimpanzee MIR4779 (100% identical).